CARD10 (caspase recruitment domain family member 10)
Description:
Scaffold protein that plays an important role in mediating the activation of NF-kappa-B via BCL10 or EGFR.
Synonyms: CARMA3; BIMP1; IMD89
Tractability: PROTAC: ubiquitination databases record sites on it.
Gene: Protein-coding gene on chromosome 22 (37,490,362 to 37,519,542, reverse strand). Ensembl gene ENSG00000100065.
Subcellular location: Cytoplasm
Subcellular location (Human Protein Atlas): Cytosol
Gene Ontology:
Molecular function: protein binding; signaling adaptor activity; signaling receptor complex adaptor activity
Biological process: activation of NF-kappaB-inducing kinase activity; negative regulation of cell migration involved in sprouting angiogenesis; positive regulation of protein localization to nucleus; positive regulation of canonical NF-kappaB signal transduction; protein-containing complex assembly; regulation of canonical NF-kappaB signal transduction; regulation of immune response; signal transduction; regulation of apoptotic process
Cellular component: CBM complex; cytoplasm
Genetic constraint (gnomAD): Loss-of-function variants: 51 observed, 95.05 expected, observed/expected ratio (o/e) 0.54, 90% interval 0.43 to 0.68. The upper end of that interval is the gene's LOEUF score, 0.68, which puts it in group 2 of 6, group 1 being the genes least tolerant of losing a copy. Missense variants: 1,192 observed, 1,231.4 expected, observed/expected ratio (o/e) 0.97, 90% interval 0.92 to 1.01. Synonymous variants: 596 observed, 511.84 expected, observed/expected ratio (o/e) 1.16, 90% interval 1.09 to 1.25.
Homologues: Orthologues: chimpanzee CARD10 (99% identical), macaque CARD10 (98% identical), pig CARD10 (93% identical), dog CARD10 (93% identical), mouse Card10 (91% identical), rat Card10 (90% identical), rabbit CARD10 (89% identical), guinea pig CARD10 (82% identical). Paralogues in human: CARD11 (38% identical), CARD14 (26% identical), CARD9 (19% identical).
Diseases named in the same sentence as CARD10 in open-access papers:
CARD10 is named in the same sentence as 43 diseases in open-access papers, as found by Europe PMC text mining. Sharing a sentence is not in itself a finding about the gene and the disease. The quoted sentences say what the papers report.
glaucoma (9 papers, 2012 to 2024). Increased pressure in the eyeball due to obstruction of the outflow of aqueous humor. "Card10 is involved in the apoptosis signaling pathway and is associated with diseases such as Primary Open Angle, Open-Angle Glaucoma, and Glaucoma." (PMID 34884814, 2021). "In addition, CARD10 rs9607469 and CARD10 rs9610775 are associated with primary open-angle glaucoma and amnestic mild cognitive impairment, respectively." (PMID 36618379, 2022). "Those rare variants are located in CYP1B1, SIX6, CARD10, MFN1, OPTC, OPTN, and WDR36 glaucoma-related genes." (PMID 38241218, 2024). "We showed that the second variant does not affect the miR-4707 biogenesis, but reduces the binding of miR-4707-3p to CARD10, a gene known to be involved in glaucoma." (PMID 29049738, 2017). "Four genes (CARD10, CWC27, RERE, and USP37) were nominally enriched (uncorrected P < 0.05) in the glaucoma cohort." (PMID 27896285, 2016).
breast carcinoma (6 papers, 2007 to 2020). "This evidence suggests that the altered expression levels of CARD10, KLF4, Acly, Atp1b1, and Spint2 may be contributing factors in the higher mortality rates of AA breast cancer patients." (PMID 17472751, 2007).
bladder cancer (5 papers, 2018 to 2024). "Caspase recruitment domain family member 10 knockdown caused a significant change in the metabolites in bladder cancer cells." (PMID 31565867, 2019). "In our previous reports, we found that CARD10 was highly expressed in bladder cancer tissue samples and cell lines." (PMID 31565867, 2019). "In the present study, we focused on the role of CARD10 in bladder cancer and analysed its downstream effect." (PMID 31565867, 2019). "We indicated that CARD10 promote bladder cancer growth via CPS1 and maybe a potential therapeutic target in bladder cancer." (PMID 31565867, 2019). "FASN, MAP2 and BMP6 were highly expressed in bladder cancer, while GPC2, CNOT6L, GALNT12 and CARD10 were expressed at low levels in bladder cancer." (PMID 38218866, 2024).
psoriasis (3 papers, 2018 to 2022). An autoimmune condition characterized by red, well-delineated plaques with silvery scales that are usually on the extensor surfaces and scalp. "Although CARD11 and CARD10 have been previously shown to contribute to lymphoid malignancies and epithelial carcinomas, respectively, CARD14 signalling has so far been mainly studied in keratinocytes in the context of psoriasis." (PMID 36009554, 2022). "This balance between CARD10 and CARD14 might be important in the context of psoriasis where keratinocyte differentiation processes are known to be dysregulated." (PMID 30386326, 2018). "In contrast to CARD10 and CARD11, CARD14-activating stimuli are still largely unclear; thus, CARD14 activation has mainly been studied in the context of CARD14 overexpression or by the use of specific CARD14 gain-of-function mutants identified from psoriasis patients." (PMID 36009554, 2022).
Arterial thrombosis (2 papers, 2017 to 2021). The formation of a blood clot inside an artery. "In addition, miR-181b and Card10 (caspase recruitment domain family member 10) were found to be important regulators of thrombin-induced EC activation and arterial thrombosis, as miR-181b overexpression inhibited thrombin-induced activation of NF-kB signaling by targeting the Card10." (PMID 33917744, 2021).
gastric cancer (2 papers, 2012 to 2017). A primary or metastatic malignant neoplasm involving the stomach. "To examine the effects of increased miR-146a levels in gastric cancer we identified two new miR-146a targets, CARD10 and COPS8, and investigated the roles of these targets." (PMID 22992343, 2012). "We found that miR-146a is up-regulated in a mouse model of gastric cancer as well as in human gastric adenocarcinomas and identified CARD10 and COPS8 as new direct targets of miR-146a." (PMID 22992343, 2012). "miR-146a expression is up-regulated in a majority of gastric cancers where it targets CARD10 and COPS8, inhibiting GPCR-mediated activation of NF-kappaB, thus reducing expression of NF-kappaB-regulated tumor-promoting cytokines and growth factors." (PMID 22992343, 2012). "In gastric cancer, in addition to its role in TLR/IL-1R signaling, miR-146a-5p has been reported to directly control the G-protein-coupled receptor-mediated activation of NF-κB, via caspase recruitment domain-containing protein 10 (CARD10) and COP9 signalosome complex subunit 8 (COPS8)." (PMID 28824448, 2017).
liver cancer (1 paper, 2025). An epithelial or non-epithelial malignant neoplasm that arises from the liver. "Following, we also check the CARMA3 (CARD10) expression in different liver cancer stages and tumor grade." (PMID 41209553, 2025).
tumor (15 papers, 2012 to 2025). "CARD10 is closely associated with tumor development because of its role in promoting tumor progression by activating NF-κB." (PMID 35008789, 2021). "The xenograft model showed that decreased expression of CARD10 inhibited tumour growth and down‐regulated CPS1 expression in vivo." (PMID 31565867, 2019). "Of note, we identified newly emerged 8 non-synonymous somatic mutations of the genes (ACAP2, CARD10, KIAA0556, PAAQR7, PPP1R39, SAFB2, STARD9, and ZFYVE9) in the imatinib-resistant tumor tissue." (PMID 23922791, 2013). "Preventing CARD10 cleavage in the lung tumor A549 cell line increased basal levels of IL-6 and extracellular matrix components in vitro, and led to increased tumor growth in a mouse xenograft model, suggesting that CARD10 cleavage by MALT1 might be a built-in mechanism controlling tumorigenicity." (PMID 33824280, 2021). "CARD10 (also known as CARMA3) mediates activation of NF-κB and tumor progression." (PMID 25644622, 2015). "This suggested that CARD10 cleavage might not contribute to tumor growth through cell intrinsic mechanisms." (PMID 33824280, 2021).
cancer (12 papers, 2011 to 2025). A tumor composed of atypical neoplastic, often pleomorphic cells that invade other tissues. "However, CARD10 is overexpressed in many cancers, which has been linked to higher aggressiveness." (PMID 33824280, 2021). "CARD10 protein mediates the occurrence and progression of various kinds of cancers." (PMID 38218866, 2024). "Knocking down CARD10 in cancer cells impairs proliferation, survival, and migration." (PMID 33824280, 2021). "The current understanding of CARD10 pathophysiological function in cancer is still limited." (PMID 33824280, 2021). "However, how CARD10 contributes to cancer processes has remained ill defined." (PMID 33824280, 2021). "CARD10, the prototypical CARD-CC protein in non-hematopoietic cells, is overexpressed in several cancers and has been associated with poor prognosis." (PMID 33824280, 2021). "In a number of cancer cell lines, miR-16 has been shown to be involved in the induction of apoptosis by targeting BCL-2 and in cell cycle regulation by targeting CDK6, CDC27, and CARD10." (PMID 21698265, 2011).
infection (3 papers, 2021 to 2023). The state of being infected such as from the introduction of a foreign agent such as serum, vaccine, antigenic substance or organism. "Analysis of mRNA levels revealed a significant decrease in expression of the miR‐146a/b direct target gene Irak1 during RV‐A1b infection and increased Card10 expression in the PBS treatment group in Mir146a/b−/− mouse lungs compared to wt mice." (PMID 34185416, 2021). "Caspase recruitment domain family member 10 (CARD10) and Mothers against decapentaplegic homolog (SMAD7) were uniquely up-regulated in the multiple infection group." (PMID 37910477, 2023).
epithelial carcinomas (1 paper, 2022). "Because the CARD14-related protein CARD10 was previously reported to contribute to other epithelial carcinomas, we also analysed its expression in PCa." (PMID 36009554, 2022).
rectum (1 paper, 2021). "Significantly higher expressions of CARD10 were observed in colon and rectum tumors compared to normal tissues." (PMID 34885061, 2021).
CARD10 also shares sentences with these, for which no sentence is quoted: colon carcinoma (5 papers); lung carcinoma (5); ovarian carcinoma (4); colorectal cancer (3); Primary Open Angle Glaucoma (3); autoimmune hepatitis (2); B-cell lymphoma (2); renal cell carcinoma (2); viral infection (2); abdominal aortic aneurysm (1); asthma (1); bladder injuries (1); bladder tumour (1); brain tumor (1); cystitis (1); glioblastoma (1); glioma (1); hepatocellular carcinoma (1); inflammatory bowel disease (1); Insulin resistance (1); liver cirrhosis (1); liver fibrosis (1); lymph node metastasis (1); lymphoma (1); metastatic tumor (1); non-small cell lung carcinoma (1); oral squamous cell carcinoma (1); pancreatic cancer (1); prostate carcinoma (1); pulmonary fibrosis (1).
A further 1 disease shares a sentence with CARD10 in 1 paper.